IL1B (interleukin 1 beta)
Diseases named in the same sentence as IL1B in open-access papers (continued):
Sharing a sentence is not in itself a finding about the gene and the disease.
Sepsis (continued). "We demonstrated that active caspase-1 which cleaves pro-IL-1β into bioactive IL-1β, was nearly absent in patients with sepsis or in volunteers receiving an LPS infusion." (PMID 21244670, 2011). "Sepsis results from a host inflammatory response to infection and is characterised by high circulating concentrations of inflammatory cytokines such as tumor necrosis factor (TNF)-α, interleukin (IL)-1β, IL-6 and IL-8." (PMID 20085628, 2010). "Given that excessive activation of IL-1β results in tissue injury and sepsis, IL-1β activity is subject to negative feedback by the IL-1RA." (PMID 19503839, 2009). "However, SAA, PCT, TNF-α, IL-1β, and CRP were serially measured on days 0, 4, and 8 in the patients and once in the controls.Töllner's sepsis score (TSS) was calculated for each patient." (PMID 19043563, 2008). "This included traditionally evaluated cytokines (IL-1β, IL-6, IL-8, IL-10 and TNF-α) and a number of cytokines that are not commonly associated with sepsis (IL-7, IL-13, IFN-γ and MCP-1)." (PMID 17448250, 2007). "Concentrations of IL-1β, IL-6, IL-7, IL-8, IL-10, IL-13, interferon-γ, MCP-1 and tumour necrosis factor-α were significantly higher in septic shock patients than in those with severe sepsis." (PMID 17448250, 2007). "In a mouse sepsis model induced by APEC and MRSA, A7 treatment significantly improved survival rates (60-80%), reduced bacterial loads in vital organs, and attenuated the systemic cytokine storm (TNF-α and IL-1β), thereby alleviating immune-mediated tissue damage." (PMID 41977454, 2026). "In sepsis, LPS binds to the TLR4-MD2-CD14 receptor on lung cells, activates the MyD88-dependent signaling pathway, promotes the ubiquitination of TRAF6 and activates the TAK1/IKKβ/NF-κB pathway, inducing the release of pro-inflammatory factors such as TNF-α and IL-1β." (PMID 41244772, 2025). "In sepsis-induced AKI models, PKM2 inhibition attenuates the activation of NLR family pyrin domain containing 3 (NLRP3) and absent in melanoma 2 (AIM2) inflammasomes, decreases the release of IL-1β, IL-18, and HMGB1 by macrophages, and ultimately improves survival outcomes." (PMID 40843128, 2025). "Additionally, even though TNF-α and IL-1β are well-known biomarkers for sepsis and VAP, previous studies did not evaluate their values at baseline, meaning the first day of intubation, but instead after a few days under mechanical ventilation." (PMID 40142568, 2025). "On the one hand, statins executed anti-inflammatory effects by modulating upstream intracellular signaling pathways, on the other hand, cytokines such as TNF, IL-1β, and IL-6, were pivotal in the manifestation of SIRS and might serve as prognostic biomarkers in sepsis." (PMID 39927168, 2025). "On the 3rd to 7th day of sepsis progression, the immune system enters a paralysis phase, characterized by a marked reduction in the expression of pro-inflammatory factors in M1 macrophages, as evidenced by decreased secretion of TNF-α, IL-1β, and other cytokines." (PMID 41488672, 2025). "In our LPS-induced sepsis model, the CL-treated mice reconstituted with SLC25A33-silenced BMDMs exhibited a higher survival rate and decreased secretion of pro-inflammatory cytokines, such as TNF-α, IL-6, and IL-1β, relative to mice reconstituted with vehicle-treated BMDMs." (PMID 40384854, 2025). "Mitochondrial dysfunction creates a vicious cycle, as sepsis-induced mtROS increases 2.5-fold to upregulate iron transporters like TFR1 while simultaneously activating NF-κB, with iron chelation reducing both mtROS and IL-1β levels by over 45% in preclinical models." (PMID 40893878, 2025). "In LPS-induced sepsis rat model, PF pretreatment inhibited PI3K/Akt/ERK-mediated HIF-1α and TLR4/MyD88/NF-κB signaling, thereby reducing inflammation by decreasing the levels of tumor necrosis factor-α (TNF-α) and interleukin-1β (IL-1β) in serum and cardiac tissue." (PMID 41311552, 2025).
Sepsis (continued). "In addition, levels of kidney function indicators (BUN and Scr) and proinflammatory factors (TNFα and IL-1β) were found to be increased in sepsis patients with AKI compared to those without AKI." (PMID 41406481, 2025). "Finally, we found that IL-1β expression correlates with expression of the complement receptor in patients suffering from sepsis, but not uninfected patients and healthy individuals." (PMID 38236896, 2024). "Together, these results indicate that expression of IL-1β, the IL-1β receptor, and the complement 3 receptor transcripts are induced in humans suffering from sepsis and that positive correlation between expression of IL-β and C3AR1 occurs only in sepsis patients." (PMID 38236896, 2024). "In humans, serum IL-1β levels are persistently increased in patients with sepsis who have outcomes of non-survival, suggesting that it may also play a role in sepsis." (PMID 39273060, 2024). "Western blot analysis revealed that in the LPS-induced sepsis model (Group 2), Nogo-A expression was significantly elevated, while the expression of proteins such as p-PERK, MFN1, NOX2, NOX4, NLRP3, p-STING, p-TBK1, and IL-1β also significantly increased, and SHP2 expression decreased." (PMID 39151100, 2024). "The lipopolysaccharide infusion induced sepsis-like inflammation with tachycardia, elevated pulmonary pressure, elevated lactate level, as well as elevated pro-inflammatory cytokines like interferon (IFN)-γ, interleukin (IL)-1β, IL-2, IL-6, IL-8, IL-12 and tumor necrosis factor alpha (TNF-α)." (PMID 39273234, 2024). "In sepsis, the mitogen-activated protein kinase (MAPK) pathway is consistently activated in conjunction with the NF-κB pathway, either independently or cooperatively stimulating the secretion of downstream inflammatory factors such as COX-2, TNF-α, IL-1β, IL-18, IL-6, and iNOS." (PMID 39267971, 2024). "Additionally, the blockade of APOH after CLP led to a significant increase in the levels of serum and peritoneal inflammatory cytokines, such as TNF-α, IL-1β, and IL-6, alongside a decrease in IL-10 levels after non-severe sepsis." (PMID 38291524, 2024). "Lastly, we found that injecting LPS in Il18−/−, Ifng−/− and Il1b−/− mice treated with TNF-neutralizing antibodies abrogated the cellular effects validated above in all cases but lung granulocytes, suggesting that other pathways are likely at play for specific processes triggered by sepsis." (PMID 38191855, 2024). "Compared with wild-type mice in CLP sepsis models, mice with FXI knockout had smaller increases in the plasma levels of inflammatory cytokines TNF-α and interleukin-10 (IL-10), delayed responses to the inflammatory cytokines IL-1β and IL-6, and a greater survival advantage." (PMID 38213768, 2024). "While we show a correlation between expression of IL-1β and the complement receptor C3AR1 in humans suffering from sepsis, it will need to be tested whether this is the mechanism which results in fatalities from septicaemia in humans." (PMID 38236896, 2024). "In sepsis-induced lung injury, it is crucial to recognize the importance of inflammatory signaling pathways, specifically the Mitogen-activated protein kinases (MAPK) and NF-κB pathways, in the excessive release of inflammatory cytokines like Tumor necrosis factor alpha (TNF-α) and IL-1β." (PMID 39867697, 2024). "Either systemic or LyzCRE specific knock-out could alleviate the severity of sepsis mice, reduce the proinflammatory cytokine TNF-α and IL-1β expression in serum and decrease the monocytes number in bronchial alveolar lavage and peritoneal lavage via flow cytometry." (PMID 36707853, 2023). "Here, after the induction of sepsis, IL-10 levels were attenuated in OSMR KO mice following the induction of FIP, as were the levels of the pro-inflammatory cytokines IL1β, IL-6, TNF, and KC, which may reflect a more balanced attenuation of inflammation with improved survival." (PMID 36831019, 2023).
Sepsis (continued). "In our study, we found that injecting parenteral ω-3 PUFA solutions reduced IL-1β, TNF-α, IL-6, IL-10, IFN-γ, and IL-17 levels and hindered the secretion of multi-organ injury markers induced by CLP treatment, indicating the protective role of ω-3 PUFAs in sepsis." (PMID 36694426, 2023). "Additionally, while TNFα, IL1β, and IFNγ are seen in human sepsis, they are considered to be pro-inflammatory cytokines, and not sepsis-specific." (PMID 37175585, 2023). "Indeed, in the setting of Gram-negative bacteremia and sepsis, the onset of myocardial depression and ventricular dilatation following an outflow of cytokines (IL1β, IL-6, and TNFα), nitric oxide, and endotoxins has been reported." (PMID 37756092, 2023). "In cases of sepsis, including bacterial sepsis and viral conditions like COVID-19 (coronavirus disease-2019), aberrant activation of the NLRP3 inflammasome has also been documented mostly through the measurement of increased plasmatic concentrations of IL-1β and IL-18." (PMID 38140660, 2023). "In our past study, we demonstrated that mice lacking stefin B were significantly more sensitive to sepsis induced by lipopolysaccharide (LPS) and secreted higher levels of interleukin 1-β (IL-1β) due to increased inflammasome activation in bone marrow-derived macrophages." (PMID 38067160, 2023). "In the process of sepsis, cytokines such as TNF-α, IL-1β, and IL-6 mediated inflammatory response plays an important role, which may lead to endothelial and epithelial damage, affect vascular permeability and heart function, and eventually result in tissue necrosis and organ failure." (PMID 38152336, 2023). "Administration of IL-1β-preconditioned UC-MSCs led to decreased serum levels of IL-6, TNF-α, alanine aminotransferase and aspartate aminotransferase, and liver, lung, and kidney injury and increased bacterial clearance and survival in experimental CLP-induced sepsis." (PMID 37007034, 2023). "To determine whether Erbin-mediated autophagy regulates sepsis-induced inflammatory response and organ injury, we investigated the level of inflammatory cytokines TNF-α, IL-6, IL-1β, HMGB1, and IL-10 in polymicrobial sepsis mice and MDP-treated BMDMs with CQ treatment." (PMID 38105228, 2023). "Therefore, it suggested that SIN might protect against sepsis-induced MI via targeting TNF-α, IL-6, and IL-1β." (PMID 37388447, 2023). "Additionally, using an ROC curve analysis, the plasma levels of IL-1β, IL-7, IL-12, IL-1RA, RANTES/CCL5, MIP1B/CCL4 and IP10/CXCL10 could help differentiate children with sepsis from both clinical malaria and febrile controls." (PMID 35811678, 2022). "A principal component analysis and a receiver operator characteristic curve analysis, identified seven potential biomarkers; IL-1β, IL-7, IL-12, IL-1RA, RANTES/CCL5, MIP1β/CCL4 and IP10/CXCL10 that could discriminate children with sepsis from clinical malaria and other febrile conditions." (PMID 35811678, 2022). "IL-1β was not down-regulated by ISO-1 in kidney, which meant that IL-1β might lack specificity for pyroptosis in sepsis-induced AKI." (PMID 35165294, 2022). "However, non-septic children had lower levels of IL-1β (1.80 for sepsis, 2.22 for non-sepsis pg/ml), but the difference was not significant." (PMID 35582414, 2022). "The elevated secretion of IL-1β and IL-18, and expression pattern of HMBOX1, NF-κB (cytoplasm), nuclear NF-κB, NLRP3, caspase-1, and GSDMD-N were all reversed by overexpression of HMBOX1, showing that sepsis-exos and miR-885-5p mimic had similar effects on AC16 cells." (PMID 35345489, 2022). "Besides, the serum levels of TNF-α, IL-1β, and IL-6 in the γ3-RBCNPs group were significantly lower than those in PBS groups, indicating that γ3-RBCNPs reduced systemic inflammatory response in mice with sepsis." (PMID 35783411, 2022).
Sepsis (continued). "LP17 has also been shown to be an effective treatment for sepsis secondary to Pseudomonas aeruginosa pneumonia in rats, resulting in with improved hemodynamic status, attenuated lactic acidosis and hypoxemia, reduced serum TNF-α, IL-1β, and IL-6, and improved 7-day survival of the septic rats." (PMID 35784361, 2022). "ELISAs showed that the protein levels of these two inflammatory cytokines (IL1β and IL6) followed similar expression patterns as the mRNA expression levels Together, these data showed that Rabeprazole treatment accelerates the resolution of sepsis-induced lung inflammation." (PMID 35563731, 2022). "Similarly, the previous studies showed that LNT reduces the activation of NF-κB and inhibits the production of pro-inflammatory cytokines IL-1β, TNF-α, IL-8 in chondrocytes, LNT intervention improves hepatic cell morphology by the decreased activity of NF-κB signal in rat’s liver with sepsis." (PMID 35313999, 2022). "Our result showed a considerable decrease in NLRP3, GSDMD-N, IL-18 protein expression, and serum IL-1β levels in the AFC and ASC groups compared to the ANC group, indicating that FMT and SCFAs can suppress cell pyroptosis and have a protective function in sepsis." (PMID 36713461, 2022). "In the early stage of sepsis, to eliminate invading bacteria, macrophages are activated to become the M1 type, which produces a large number of proinflammatory factors, such as tumour necrosis factor (TNF)-α, interleukin (IL)-6, IL-1β, type I interferon, and chemokines." (PMID 34627385, 2021). "IL-1b is not detected in all septic patients but is an indicator of sepsis severity." (PMID 33917002, 2021). "In murine models of polymicrobial sepsis induced by CLP, and endotoxic shock induced by lipopolysaccharide (LPS), blockade of IL-27 with neutralizing anti-IL-27p28 antibodies decreased inflammatory cytokine levels (IL-1β, IL-17 and IFN-γ), and improved the survival rate." (PMID 34079555, 2021). "However, in those who are classified as critical and already suffering from sepsis, aaPRP was not able to lower IL-1β concentration." (PMID 34306796, 2021). "However, our experiments with SAMP8 showed that LTP was not impaired despite the remarkable elevation in IL-1β during sepsis, and that basal synaptic transmission was reduced instead." (PMID 33643027, 2021). "In addition, the concentrations of pro‐inflammatory cytokines TNF‐α, IL‐1β, IFN‐γ and IL‐6 in circulation were prominently repressed after wogonin treatment in these two types of sepsis mice, with the levels of these cytokines gradually decreased as the dose of wogonin increased." (PMID 33982381, 2021). "Il-1b is not normally identified in the serum but is detected in the serum of patients with sepsis." (PMID 33917002, 2021). "Initially, sepsis was induced by performing CLP in mice, after which the mouse models presented significant myocardial depression, injury and inflammation, showing as decreased MAP, LVSP and ±dp/dtmax values, and increased cTnI, CK-MB, TNF-α, IL-6, IL-1β and NO levels in mice." (PMID 33645622, 2021). "In contrast, cardiac Il1b expression in sepsis was independent of the genotypes." (PMID 34472725, 2021). "Several sepsis studies investigate the interaction of melatonin with NLRP3 in mouse hearts, where sepsis activates the NLRP3 inflammasome and melatonin injection suppresses this activity, confirmed by a decrease in the levels of mature caspase-1 and IL-1β, NLRP3, and ASC." (PMID 34202842, 2021). "In a mouse model of cecal ligation and puncture (CLP) sepsis, rGas6 treatment reduced lung serum levels of proinflammatory cytokines, such as IL-6 and IL-17, and mRNA levels of proinflammatory cytokines and chemokines, such as TNF-α, IL-1β, IL-6, IL-17, and MIP-2, at 20 h post-CLP." (PMID 34829903, 2021).
Sepsis (continued). "She reported that applied OMVs from sepsis sepsis-inducing bacteria in contrast to non-sepsis sepsis-inducing bacteria significantly reduced the activity of RNase1 and promoted endothelial cell activation, as indicated by increased IL-8, CXCL10, ICAM-1, and IL-1β expression." (PMID 39697663, 2021). "Moreover, PDK1 deletion could decrease the levels of IL-1β and IFN-γ in the late stage of sepsis, as the opposite of early stage." (PMID 32774145, 2020). "NB 06, like chloroquine, modulates the gene expression of the prominent inflammatory messengers IL-1B, IL-23A, CCL4, CCL20, and IL-6; likewise, it has beneficial effects in (systemic) infections involving bacterial endotoxins, such as LPS, by targeting the TLR4 receptor pathway in sepsis." (PMID 32668803, 2020). "We here demonstrate that blood leukocytes of hospitalized CAP patients display an impaired release of TNF-α, IL-1β, IL-6, and IL-10 as well as an heightened production of IL-1RA in response to stimulation with LPS and K. pneumoniae, regardless of the presence of sepsis." (PMID 32477337, 2020). "Sepsis and hemorrhagic shock result from accumulation of monocytes and activated neutrophils in various organs where they produce large amounts of cytotoxic cytokines (e.g., TNF and IL-1β), reactive oxygen species, and reactive nitrogen species which cause organ damage and, ultimately, death." (PMID 32027657, 2020). "Although neutralization of TNF-α or interleukin 1 β (IL-1β) did not reduce mortality in sepsis trials, experimental and clinical data have shown that these proinflammatory cytokines with specific relevance for innate immune functions are important mediators of severe sepsis." (PMID 32670276, 2020). "For the proinflammatory cytokines, the levels of IL-1β, IL-2, IL-6, and TNF-α were elevated in the early sepsis phase (2 h), but most other proinflammatory cytokines, including IL-12, IL-15, IL-17, and IFN-γ, showed significant elevation in the late sepsis phase (24–48 h)." (PMID 31354717, 2019). "During sepsis ASC specks may be released from pyroptotic monocytes, other activated leukocytes, endothelial cells, or cardiomyocytes, that have all shown to release IL-1β in sepsis." (PMID 31221993, 2019). "Biomarkers of inflammation and sepsis investigated in foals and adult horses include lactate, soluble CD14 (sCD14), serum amyloid A, procalcitonin, C-reactive protein (CRP), haptoglobin (Hp), interleukin 1β (IL-1β), interleukin-10 (IL-10), and interleukin-6 (IL-6)." (PMID 30931316, 2019). "Lnc‐THRIL relative expression was positively correlated with levels of CRP (r = 0.421, P < 0.001), PCT (r = 0.251, P = 0.008), TNF‐α (r = 0.357, P < 0.001), and IL‐1β (r = 0.305, P = 0.001), but not correlated with IL‐17 level (r = −0.072, P = 0.459) in sepsis patients." (PMID 31257645, 2019). "Nevertheless, excessive systemic levels of IL-1β are involved in the pathogenesis of various inflammatory disorders, including rheumatoid arthritis, gout, transplant rejection, periodic fever, systemic inflammatory response syndrome (SIRS), sepsis, and multi organ dysfunction syndrome (MODS)." (PMID 31019507, 2019). "During sepsis, endotoxin lipopolysaccharides (LPS) activate toll-like receptor 4 (TLR4) signaling pathway and further induce translocation of nuclear factor-kappa B (NF-kappa B) to modulate expression of pro-inflammatory genes, including TNF-α, IL-6, and IL-1β." (PMID 30083155, 2018). "We first characterized PAXgene samples of 20 sepsis patients and ten healthy controls with respect to expression of the “immunosuppressive” miRNA signature and mRNA-levels of anti-inflammatory IL4, IL10, TGF-ß and pro-inflammatory “master cytokine” interleukin 1 beta (IL-1β)." (PMID 30332984, 2018).